ROR2 (ROR family WNT receptor 2)
Diseases named in the same sentence as ROR2 in open-access papers (continued):
Sharing a sentence is not in itself a finding about the gene and the disease.
tumor (continued). "However, it is unclear whether TAMs produce sufficient levels of ROR2 to respond to WNT5A or whether they rely on CAF-transferred ROR2 similar to tumor cells." (PMID 37722040, 2023). "However, it remained unknown whether WNT11 can also interact with ROR2 in humans and whether it might be responsible for its tumor-supporting function." (PMID 34911552, 2021). "Therefore, ROR2 may dominate in either of the two arms of downstream Wnt signalling depending on the tumour context." (PMID 33494187, 2021). "However, a recent study reported a reduction in tumor motility and invasiveness upon ROR2 overexpression, again raising the question whether the regulation of ROR expression levels is critical for determining their functional impact." (PMID 33445713, 2021). "Finally, tumor xenograft experiment showed ROR2 overexpression could significantly repress the growth rate and volume of transplanted tumors." (PMID 31878941, 2019). "A likely explanation for this difference in findings may be the differences in the biological models used, as the previous publication which reported increased AXIN2 expression following ROR2 silencing used in vivo mouse models incorporating the tumour microenvironment." (PMID 27440078, 2016). "Having already metastasised to a secondary site, SW620 cells would possess a markedly different genetic composition than that of a primary tumour and may be resistant to any functional effects resulting from restoration of expression in an early gene target such as ROR2." (PMID 27440078, 2016). "However, the expression of Ror2-DM in 786-0 cells abrogated the increased tumor growth seen with wild-type Ror2, suggesting that this domain retains a component of the activity for Ror2 to promote tumor growth." (PMID 25542006, 2014). "Given their roles in tumor progression, both AXL and ROR2 have emerged as promising targets for CAR-T therapies." (PMID 40677703, 2025). "To investigate the potential tumor-promoting role of ROR2 via the PI3K/AKT pathway in MB cells, we designed three specific siRNAs targeting ROR2." (PMID 38632356, 2024). "Collectively, these findings underscore that ROR2 plays a pivotal role in mediating epithelial–mesenchymal transition (EMT) in MB, influencing tumor invasiveness, metastatic potential, and overall disease progression." (PMID 38632356, 2024). "Specifically, we found that the WNT signaling cell surface receptor ROR2 represented a robust and genuine marker of all ALK+ ALCL patient tumor samples." (PMID 35246138, 2022). "We identified WNT11 as a ligand for human ROR2 that activates WNT/PCP signaling and is responsible for the induction of tumor invasion." (PMID 34911552, 2021). "Although some sarcomas subtypes express tumor epitopes, such as HER2, GD2, ROR2, or EGFRvIII, B7‐H3, or oncofetal glycosaminoglycans, these tumor epitopes are often only expressed at low levels." (PMID 33047515, 2020). "A total of 76 mRNAs was correlated to lncRNA NR_046683, including ROR2, MTBP and ATP2C2, which are tumor-related protein-coding genes." (PMID 30766487, 2019). "ROR2 has also been found to antagonize AKT signaling, thus inhibited the growth, invasion and migration of tumor cells." (PMID 31878941, 2019). "The IHC results showed a correlation between the expression of Wnt5a, Ror2 and CTHRC1 with high histological grade of the tumor, while E-cadherin showed an opposite trend of expression." (PMID 28427201, 2017). "We also confirmed that IFT20 mediates the effect of Ror2 signaling in these tumor cells, as the ectopic overexpression of IFT20 reverted the effect of siRNA against Ror2." (PMID 28127051, 2017). "The results indicated that higher expression of Wnt5a and ROR2 were found in ADC and SCC tissues than that in the matched, adjacent non-tumor tissues." (PMID 29054966, 2017). "Thus, the function of PTK7 and Ror2 may depend on tumor context and ultimately on receptor context." (PMID 26680417, 2015).
tumor (continued). "The high ROR2 protein expression was detected in 45.68% (74/162) of PDAC tissue samples, which was higher than in matched tumor-adjacent tissue and benign pancreatic disease tissues samples." (PMID 26259918, 2015). "Relative expression of ROR2 and Wnt5a mRNA in NSCLC and matched tumor-adjacent tissues were quantified by quantitative reverse transcriptase polymerase chain reaction (qRT-PCR)." (PMID 26305508, 2015). "Pre-clinical studies showed potent, selective lysis of ROR2-expressing cell lines and durable tumor regression in xenograft models, while non-human primates tolerated single doses up to 10 mg/kg with good systemic stability." (PMID 41375018, 2025). "The expression of ROR2 in HCC tumor samples was positive in 147 patients (60.5%) and negative in 96 patients (39.5%)." (PMID 37814183, 2024). "We analyzed the I-SPY2 transcriptome dataset of baseline pretreatment tumor specimens for expression of ROR1 and ROR2 as a transcriptome dataset for post-neoadjuvant surgical tumor tissue is not yet available." (PMID 37029329, 2023). "Potential limitations of our study include the analysis of pretreatment tumor specimens only, analysis of gene expression only, and use of Agilent 44 K platform which cannot distinguish between RNA isoforms of ROR1 or ROR2 that can or cannot be expressed as cell surface proteins." (PMID 37029329, 2023). "The underlying reasons for this discrepancy have not been elucidated and ROR2 has been considered alternatively an oncogene or a tumor suppressor gene depending on the tumor type." (PMID 36127680, 2022). "This study confirms mRNA expression of both ROR1 and ROR2 (albeit low levels) in non-diseased human tissues and hence, on-target off-tumour effects of targeted therapy need to be closely monitored." (PMID 36289823, 2022). "For ROR2, similar to non-diseased tissues, ROR2-v1 was the most highly expressed isoform in all 33 different tumour types profiled by TCGA." (PMID 36289823, 2022). "We hypothesized that samples in the dataset GSE19069, which are characterized by reduced ROR2 expression levels in ALK+ ALCL, were comprised of tissues with fewer tumor cell infiltrates." (PMID 35246138, 2022). "Activation of ROR1 and ROR2 was shown to result in the phosphorylation of PI3K, AKT, cAMP response element-binding protein (CREB), and mTOR as well as its downstream targets S6 and 4EBP1 in numerous tumor entities." (PMID 33445713, 2021). "In most of them, high levels of ROR2 correlated with increased tumorigenic properties, such as proliferation, migration, invasion, anchorage-independent growth, epithelial-to-mesenchymal transition (EMT), and in vivo tumor development." (PMID 34774050, 2021). "Compared to the tumour tissue, normal samples showed lower expression of ROR1 or ROR2." (PMID 32807831, 2020). "To expand our knowledge to additional cell lines, we measured the expression level of Ror2 protein in several normal/tumor prostatic cell lines and found that the two genetically-related RWPE-1 and -2 cell lines respectively expressed low versus high levels of Ror2 mRNA and protein." (PMID 32484838, 2020). "Then intimate connection with Wnt family indicates that ROR2 regulates tumor biological behavior through canonical or non-canonical Wnt signaling pathway, and additional downstream effectors include Rho-family GTPases, JNK cascade, and the like." (PMID 31878941, 2019). "Thus, as in the case for tumor invasion and invadopodia formation, as well as the regulation of Golgi structure, IFT20 also mediates the regulation of Golgi-derived MTs by Ror2 signaling." (PMID 28127051, 2017). "The mean ROR2 expression in the tumor tissues was 1.886-fold higher than in non-malignant tissues (P = 0.016)." (PMID 26259918, 2015). "Restoration of ROR2 expression in DLD1 cells resulted in a marked reduction of tumour formation in vivo; at the time the mice were sacrificed, DLD1 tumours expressing ROR2 had on average half the volume of those lacking ROR2 activity." (PMID 20591152, 2010).
tumor (continued). "The results confirmed that tumours lacking ROR2 expression presented promoter hypermethylation and lack ROR2 protein." (PMID 20591152, 2010). "We investigated the expression of ROR2 in our tumours but found no consistent pattern of expression, with as many cases showing downregulation as increased expression (data not shown)." (PMID 18414471, 2008). "Similarly, ROR2, an orphan tyrosine kinase receptor critical during embryogenesis, exhibits limited expression in adult tissues but is aberrantly upregulated in RCC, where it contributes to enhanced tumor growth, migration, and invasiveness." (PMID 40677703, 2025). "In vivo, verteporfin treatment effectively reduced tumor burden in the HR xenograft models, decreased p-STAT3 and PD-L1 expression, and increased apoptosis, underscoring the therapeutic potential of targeting the ROR2-YAP/TEAD axis to overcome trastuzumab resistance." (PMID 40542295, 2025). "Similarly, migration and invasion assays using transwell chambers revealed a significant decrease in the number of tumor cells that traversed to the lower chamber, with or without matrigel, across all three MB cell lines when ROR2 was silenced." (PMID 38632356, 2024). "ROR2 acts either as a tumor suppressor or an oncogene depending on the tumor type, but, to our knowledge, it has never been shown to play both roles in the same tumor type." (PMID 34774050, 2021). "Notably, although ROR2 levels were not increased in tumor samples, high ROR2 expression was correlated with lower OS (HR = 1.5; Log-rank p = 0.046)." (PMID 33869179, 2021). "Therefore, it promotes that the use of therapies against ROR2 to be preceded by studies intended to rule out anti-tumor effects of ROR2 in said tumor type." (PMID 34774050, 2021). "As proposed for ROR2, WNT5A might also have either a tumour-promoting or-suppressing role." (PMID 20591152, 2010). "This pattern was also observed regardless of whether the tumor was classified as primary or metastatic except in Primary tumors when segmenting by ROR2 where high ROR2 expressors had a significantly higher prevalence of PDL1+ tumors as compared to low expressors (29.6% vs. 19.3%, p = 0.002)." (PMID 38558536, 2024). "It is also possible that although Ror2 expression did not alter cell proliferation under in vitro culture conditions, that Ror2 expressing cells in vivo may be presented with additional signaling cues leading to signaling cascades enhancing tumor growth." (PMID 25542006, 2014). "For the matched normal and tumour tissues (n = 19), the expression level of ROR1 or ROR2 was significantly different between tumour and adjacent normal tissues." (PMID 32807831, 2020). "While our previous studies have shown that suppression of Ror2 in RCC cells did not alter cell proliferation in vitro, the increases in tumor size observed in wild-type Ror2 overexpressing xenografts may be the result of several possibilities." (PMID 25542006, 2014).
skeletal dysplasia (5 papers, 2010 to 2024). Any Mendelian diseases that affects growth and development of the skeleton. "Deletion of Ror2 in mesenchymal progenitors of cartilage and bone leads to significantly more severe skeletal dysplasia compared to Ror2 loss in Osx-expressing cells." (PMID 37307827, 2024). "Mutations in the ROR2 gene in humans have been identified as the cause of recessive RS, which is characterized by severe skeletal dysplasia, including generalized limb bone shortening, segmental spine defects, brachydactyly, and distinctive facial features." (PMID 37307827, 2024). "The lead SNP rs4275276 is an intron variant of ROR2, in which mutations were found to cause a severe skeletal dysplasia known as Robinow syndrome-1 (OMIM 268310)." (PMID 33983923, 2021). "In this study, we investigated the role of Ror2 in limb morphogenesis and its connection to RS, a rare genetic disorder characterized by skeletal dysplasia." (PMID 37307827, 2024). "The mutants with Ror2 loss in early limb bud mesenchyme, but not in the osteoblast progenitors, showed short stature and arched skull with chondrodysplasia and skeletal dysplasia similar to symptoms observed in RS patients." (PMID 37307827, 2024).
infection (3 papers, 2020 to 2025). The state of being infected such as from the introduction of a foreign agent such as serum, vaccine, antigenic substance or organism. "Conversely, CpG sites related to Slc11a1, Havcr2, Ccl11, Ccl12, Sirt1, Ifng, Ccl3, Ror2, and Trem2 maintained lower methylation levels throughout the infection compared to noninfected samples." (PMID 40170749, 2025). "Knockdown of noncanonical pathway coreceptors ROR1 and ROR2 resulted in impaired infection as well, although to a lesser degree." (PMID 33883266, 2021).
colorectal (1 paper, 2016). "Together, the clinical data along with the analysis and experimentation of cell lines provides strong evidence that epigenetic silencing of ROR2 through promoter hypermethylation occurs early in colorectal carcinogenesis." (PMID 27440078, 2016).
haematopoietic cancers (1 paper, 2010). "As we show here for ROR2, WNT5A repression in colon and haematopoietic tumours is mediated by aberrant promoter hypermethylation." (PMID 20591152, 2010).
neurodegenerative disease (1 paper, 2022). A disorder of the central nervous system characterized by gradual and progressive loss of neural tissue and neurologic function. "Wnt5a- or Wnt11-Ror2 signaling can mediate IL-1β-induced neuronal cell death, suggesting that Ror2-mediated signaling might promote the pathology of the neurodegenerative diseases." (PMID 35493090, 2022).
ROR2 also shares sentences with these, for which no sentence is quoted: hepatocellular carcinoma (7 papers); leiomyosarcoma (4); multiple myeloma (4); brachydactyly type B1 (3); acute lymphoblastic leukemia (2); bladder cancer (2); endometrioid ovarian cancer (2); genetic disorders (2); hematologic malignancies (2); medulloblastoma (2); oral cancer (2); renal fibrosis (2); Ureteral obstruction (2); 3-methylglutaconic aciduria (1); acute lung injury (1); Alzheimer disease (1); arteriosclerosis (1); autosomal dominant Robinow syndrome (1); bladder urothelial carcinoma (1); Carpenter syndrome (1); ciliopathies (1); congenital myasthenic syndrome (1); coronary artery disease (1); Duchenne muscular dystrophy (1); dysplasia (1); endometrioid tumor (1); esophageal adenocarcinoma (1); Familial exudative vitreoretinopathy (1); fragile X syndrome (1); Fuhrmann syndrome (1).
A further 26 diseases each share a sentence with ROR2 in 1 paper.